TNIP1 (TNFAIP3 interacting protein 1)
Diseases named in the same sentence as TNIP1 in open-access papers (continued):
Sharing a sentence is not in itself a finding about the gene and the disease.
cancer (10 papers, 2015 to 2026). A tumor composed of atypical neoplastic, often pleomorphic cells that invade other tissues. "The genes BLK, CDC247, CSK, IRF5, STAT1, STAT4, and TNIP1 are associated with AIDs, and CDC37, DDX6, HSPA6, MAPT, PPIB, STAT1, and STAT4 are associated with cancers." (PMID 40429780, 2025). "The genes BLK, FAM167A, STAT1, STAT4, TNPO3, and TNIP1 are associated with AIDs, and CDC37, DDX6, MAPT, STAT1, STAT4, and UBE3A are associated with cancers." (PMID 40429780, 2025).
infection (10 papers, 2015 to 2024). The state of being infected such as from the introduction of a foreign agent such as serum, vaccine, antigenic substance or organism. "Infection of rTNIP1 in HaCaT cells led to a 2.3–fold increase in the mRNA level and a 9.6-fold increase in the protein level of TNIP1." (PMID 26046540, 2015). "Several SNPs were associated with susceptibility to infection and septic shock, one in the univariate analysis (rs6853 at MyD88 gene) and seven with the multivariate model (rs610604, rs6922466, rs7753394, and rs583522 at TNFAIP3 gene; rs6579837, rs73272842, rs3792783 at TNIP1 gene)." (PMID 30813592, 2019).
immune diseases (3 papers, 2019 to 2020). "Several TNIP1 SNPs have been associated with immune diseases." (PMID 30813592, 2019).
renal disorder (3 papers, 2010 to 2025). "For TNIP1, the SNP rs7708392 was also observed to be associated with onset age as well as several subphenotypes, including malar rash, renal disorder, immunologic disorder and antinuclear antibody (OR = 0.75 to 0.76, P = 0.017 to 0.043)." (PMID 22087647, 2011). "However, preferential association of TNIP1 with renal disorder and anti-dsDNA antibody was suggested by comparison with healthy controls." (PMID 20849588, 2010). "As for TNIP1, the minor allele of rs7708392 was associated with a few SLE subphenotypes including malar rash, renal disorder and antinuclear antibody, which were also observed in the Japanese population." (PMID 22087647, 2011). "In view of this, our findings could be interpreted such that polymorphisms in TNIP1-TNFAIP3 pathway might play a significant role in the subset of SLE characterized by renal disorder and anti-dsDNA antibody, but not in the subset with neurologic disease." (PMID 20849588, 2010). "We next analyzed whether TNIP1 was associated with clinical subsets such as presence or absence of renal disorder, neurological disease, serositis, anti-dsDNA antibody, anti-Sm antibody, as well as the age of onset (< 20 yr)." (PMID 20849588, 2010). "TNIP1 (TNFAIP3-interacting protein 1), exerting similar anti-inflammatory function as TNFAIP3, shows a trend toward upregulation in the glomerular compartment in human kidney diseases." (PMID 40072109, 2025).
connective tissue disorder (1 paper, 2011). A disease involving the connective tissue. "Because of its biological relevance, and previous reports of genetic association at this locus with other connective tissue disorders, we investigated TNIP1 expression." (PMID 21750679, 2011). "Because of its biological relevance, and previous reports of genetic association at this locus with connective tissue disorders, we investigated TNIP1 expression." (PMID 21750679, 2011).
TNIP1 also shares sentences with these, for which no sentence is quoted: inflammatory bowel disease (4 papers); Splenomegaly (4); colitis (3); bacterial infections (2); colorectal cancer (2); dementia (2); leukaemia (2); multiple sclerosis (2); neurologic disorder (2); scleroderma (2); adenoma (1); allergic disease (1); astrocytoma (1); atopic dermatitis (1); autoimmune hepatitis (1); Behçet’s disease (1); brain diseases (1); breast carcinoma (1); cardiac hypertrophy (1); cardiovascular disease (1); Cerebral ischemia (1); coeliac disease (1); complication (1); deficiencies (1); enteritis (1); enterocolitis (1); hematologic disorder (1); hepatitis C virus infection (1); hepatocellular carcinoma (1); HIV-1 infection (1).
A further 24 diseases each share a sentence with TNIP1 in 1 paper.